STAT6 (signal transducer and activator of transcription 6)
Diseases named in the same sentence as STAT6 in open-access papers (continued):
Sharing a sentence is not in itself a finding about the gene and the disease.
allergic disease (44 papers, 2008 to 2025). An immune response that occurs following re-exposure to an innocuous antigen, and that requires the presence of existing antibodies against that antigen. "Several pathologies, including inflammatory or autoimmune disorders, allergic diseases, as well as cancer, are associated with dysregulated Th1/Th2 equilibrium and related to inadequate expression/activity of STAT6." (PMID 41409600, 2025). "Rare gain‐of‐function mutations in STAT6 cause severe early‐onset allergic diseases, including food allergy." (PMID 40693699, 2025). "Several pathologies, including inflammatory disorders, autoimmune/allergic diseases, metabolic syndrome as well as cancer, are associated with a dysregulation of type 2 immunity related to inadequate expression and/or activity of STAT6." (PMID 41409600, 2025). "Dysregulation of STAT6 has been linked to conditions such as allergies and asthma, where an overactive Th2 response contributes to disease pathology." (PMID 39353898, 2024). "We present a combination of clinical, genetic, molecular, and transcriptional evidence of a new human disorder caused by germline AD GOF STAT6 variants in 16 patients with life-long severe allergic disease." (PMID 36884218, 2023). "Mechanistic investigation is warranted to understand how the RBP-occupied region containing a highly probable causal SNP for allergy regulates STAT6 expression and T cell biology in the context of allergic responses." (PMID 38062486, 2023). "In aggregate, these data suggest that the STAT6 germline monoallelic variants identified in the patients underlie severe allergic disease by a GOF mechanism." (PMID 36884218, 2023). "Our study expands this appreciation of the role of STAT6 in human disease by establishing that heterozygous GOF variants cause a monogenic form of severe allergic disease." (PMID 36884218, 2023). "Very recently, a report was published describing a father and his two sons with severe allergic disease who were all heterozygous for the GOF STAT6 variant p.E377K." (PMID 36884218, 2023). "This new family shares many of the features we report in our cohort of 10 families, further emphasizing that patients with early onset severe allergic disease should be assessed for underlying monogenic gene defects, including STAT6." (PMID 36884218, 2023). "SNP rs1059513 in the 3′UTR of STAT6 had a PICS2 probability score 0.985 for association with allergy, making it by far the most likely causal variant in the locus for this trait." (PMID 38062486, 2023). "In that context, a polymorphism in STAT6, a transcription factor involved in both IL-4 and IL-13 production, has been associated with allergic diseases." (PMID 34066544, 2021). "In accordance with our results, in an allergic disease model, a high number of Treg cells in the lungs and spleens in STAT6−/− mice, compared to WT animals, were associated with a decreased allergic response." (PMID 33919941, 2021). "It has been shown that a TSLP deficiency can attenuate allergic reactions by the down-regulation of STAT6 in mast cells." (PMID 27863430, 2016). "Thus, as a key transcription factor for the induction of Th2-type allergic inflammation, STAT6 increases susceptibility to allergic inflammation and its role in many allergic diseases had grabbed the attention of many researchers." (PMID 29333181, 2017). "Mice expressing constitutively active STAT6 are predisposed to allergic disease." (PMID 26466682, 2015). "STAT6 deficiency could also have other Treg-stabilizing effects such as inhibition of the IL-4 mediated conversion of iTregs to Th2-like effector T cells that typically occurs in allergy settings." (PMID 38700792, 2024). "Genetic variation in the STAT6 gene may be associated with predisposition to allergic diseases." (PMID 34066544, 2021). "Further gene-disease enrichment analysis revealed STAT6 was enriched in various allergic diseases, most notably in AA, with a strength of 1.86 and an FDR P-value of 1.8e-13." (PMID 38773393, 2024).
allergic disease (continued). "In allergic diseases, STAT6 overactivation can lead to heightened Th2 responses, with specific lncRNAs potentially contributing to this process by enhancing STAT6 activity." (PMID 39353898, 2024). "Previous studies have suggested that KAT5 contributes to chronic inflammatory responses, such as rheumatoid arthritis (RA) and allergy, by regulating the Foxp3 expression in regulatory T cells and STAT6 expression in B cells, respectively." (PMID 38110429, 2023). "STAT6 GOF is a multisystem disorder characterized by its key symptoms early-onset multiple severe food allergic disease and severe treatment-resistant atopic dermatitis." (PMID 37140667, 2023). "Population genetics provide further support for the central role that STAT6 plays in the development of human allergic disease." (PMID 36884218, 2023). "It has been proven through mice knockout studies that STAT6 is required for allergy development; however, the genetic profile activated varies greatly between cell types." (PMID 34948449, 2021). "The roles of STAT6 signal in allergy, immune regulation, tumorigenesis, and renal fibrosis have been documented." (PMID 33192584, 2020). "The purpose of this study was to {investigate the effects that n-3 and n-6 fatty acids have on STAT6 phosphorylation pathway, which leads to IgE production in B lymphocytes resulting into allergy." (PMID 26861314, 2016). "The information mirrors the importance of STAT6 in the pathogenesis of Th2 polarization and the pathogenesis of allergic diseases." (PMID 26899911, 2016). "A novel inhibitor of STAT6, PM-242H, inhibited initiation of allergic disease induced by airway fungal challenge, reversed established allergic airway disease in mice, and blocked salmeterol-dependent enhanced allergic airway disease." (PMID 26605551, 2015). "We demonstrate that salmeterol aberrantly promotes activation of the allergic disease-related transcription factor signal transducer and activator of transcription 6 (STAT6) in multiple mouse and human cells." (PMID 26605551, 2015). "STAT6, previously implicated in AD GWAS has recently gained attention as a source of rare gain-of-function (GOF) variants that result in a severe, early-onset broad allergic disease phenotype." (PMID 38920356, 2024). "Given this, it has been suggested that patients with severe early-onset allergic disease may benefit from early STAT6 GOF assessment." (PMID 38920356, 2024). "Consequently, STAT6 is involved in the pathophysiology of atopic diseases such as allergy, asthma, or atopic dermatitis." (PMID 37140667, 2023). "Finally, STAT6 inhibitors are being developed and are logical candidates for allergic disease because of the important role STAT6 plays in IL-4 and IL-13 signaling." (PMID 36230993, 2022). "STAT6 is involved in B-cell differentiation, IgE class switching, and MHC class II production; therefore, STAT6 is associated with IgE production and the progression of allergic diseases." (PMID 36476273, 2022). "IgE-dependent degranulation has been explored in STAT6 deficient mice, showing a reduction in the late phase of allergic reaction, cytokine production (IL-6, TNF alpha) rather than in the early phase." (PMID 34066544, 2021). "Whilst STAT6 activates allergy symptoms, IRSs are involved with cellular proliferation." (PMID 34948449, 2021). "When considering the harmful effects arising from excess IL-4 and IL-13, in for example allergies, knowledge of the structural and functional characteristics of the IL-4 receptors and their unique signaling via STAT6 has been useful in efforts to therapeutically modify IL-4/IL-13 biology." (PMID 29930549, 2018). "We further introduce a new class of peptidomimetic agent embodied in PM-242H that overcomes the pro-inflammatory potential of LABAs by antagonizing STAT6 activation and which might be therapeutically useful in diverse allergic disease contexts." (PMID 26605551, 2015).
allergic disease (continued). "The association between LPP and allergy may be mediated by an effect on the expression of BCL6 (B cell lymphoma 6), a transcription factor that represses the STAT6-mediated response to IL-4 and IL-13 and IgE class switching and inhibits Th2 cell differentiation in a mouse model." (PMID 32082391, 2020). "Among many allergic diseases, PARP14 interacted with STAT6 to enhance IL-4-induced gene expression in T cells, thereby promoting Th2 differentiation." (PMID 37650946, 2023). "Concomitantly, Th9 and, partially, Th2 cells—revealed by Stat6 expression and STAT5 phosphorylation —were decreased in both infection and allergy, while Th17 and Treg cells were unaffected and Th1 cells increased." (PMID 28090087, 2017). "We also included two soluble cytokine receptors (sIL4RA and sIL13RA2) and an exploratory component consisting of three allergy-related transcription factors (FOXP3, STAT3 and STAT6)." (PMID 26352148, 2015). "Given that the STAT6 axis is critical for the differentiation of TH2 cells, a subset of CD4+ helper T cells that is a major contributor to the pathogenesis of allergic disease, we next investigated TH2 signatures in these patients." (PMID 36884218, 2023). "In naïve CD4+ T cells, which express a moderate level of GATA3 mRNA after receiving signals via the T cell receptors (TCRs) in the presence of IL-4, activated STAT6 proteins bind to the GATA3 gene locus, driving Th2 differentiation, which is a characteristic in the development of allergy." (PMID 33193294, 2020). "Based on our findings of higher phosphorylation of STAT6, and higher expression of IL-4Rα, we selected the JAK inhibitors, ruxolitinib and tofacitinib, and the anti–IL-4Rα antibody, dupilumab, as drugs to test in vitro as they are all used clinically for treatment of allergic disease." (PMID 36884218, 2023). "Thus, an imbalance between STAT6 and BCL6 may be critically involved in the development of allergic diseases because BCL6 contributes to the function of a wide range of cells, including T cells, B cells, macrophages, mast cells, and airway epithelial cells." (PMID 23282478, 2008).
colitis (41 papers, 2013 to 2025). Inflammation of the colon. "Persistent activation of STAT6 is responsible for promoting the local pro-inflammatory response to favor the development of colitis-associated colon cancer." (PMID 34741044, 2021). "To directly confirm increased susceptibility to DSS-induced colitis, we examined the acute inflammatory response in WT and Stat6−/− mice after the first cycle of DSS on day 15 of the colitis-associated carcinogenesis (CAC) model." (PMID 30353167, 2019). "To determine Stat6 function during colitis-associated carcinogenesis, we subjected animals from both genotypes to the well-established AOM/DSS model." (PMID 30353167, 2019). "Compatibly, STAT6-deficient mice are relatively protected from oxazolone-induced colitis, which is accompanied by a reduction of Th2 cytokines." (PMID 26938566, 2016). "In a murine model of colitis carcinogenesis, STAT6-deficient (Stat6−/−) mice exhibited fewer and less aggressive tumors, which was associated with a decrease in the mobilization of inflammatory monocytes (CD11b+Ly6Chi) and granulocytes (CD11b+Ly6G+) compared with wild-type animals." (PMID 36768437, 2023). "In this study, we have examined whether modulating STAT6 activity and favoring an anti-inflammatory microenvironment with Trimethylglycine may enhance the response to 5-FU in already established colitis-associated colon cancer (CAC)." (PMID 32244885, 2020). "The increased tumorigenesis found in these mice at the end of the CAC model along with the results obtained with Stat3ΔIEC; Stat6−/− mice support the concept that tumor formation and growth in Stat6-deficient mice is promoted by Stat3 activation in enterocytes at the earlier DSS-induced colitis." (PMID 30353167, 2019). "Increased sensitivity to DSS-induced colitis was caused by elevated cell death in response to the initial carcinogen exposure as Stat6 deficiency led to increased chromatin compaction affecting DNA damage response in IEC upon treatment with alkylating agents independently of IL-4Rα engagement." (PMID 30353167, 2019). "We found that Stat6−/− mice developed more tumors in the colitis-associated carcinogenesis model." (PMID 30353167, 2019). "During DSS-induced colitis Stat6 loss triggers enhanced IEC apoptosis, causing intense tissue damage and massive inflammatory response, with secretion of many pro-inflammatory chemokines and cytokines that later activate intestinal epithelial cell-intrinsic survival mechanisms." (PMID 30353167, 2019). "Consequently, Stat6 suppresses colitis-associated tumorigenesis, protecting the intestinal epithelium from apoptosis and severe tissue damage." (PMID 30353167, 2019). "Moreover, STAT6 critically mediates the pro-inflammatory properties of the Th2 signature cytokine IL-4 in murine colitis, causes IL-4-dependent inhibition of Foxp3 and, thus, reduced Treg induction." (PMID 26938566, 2016). "Additionally, STAT6-deficient induced regulatory T cells (STAT6-/- iTregs) exhibited prolonged stability and suppressive efficacy in vitro and during the early stages of a colitis-associated cancer model." (PMID 38700792, 2024). "Moreover, also in response to DSS Stat6-deficient epithelia expressed more cleaved caspase 3 positive cells on day 8 of the AOM/DSS model supporting the notion that the increased inflammatory response observed in Stat6−/− mice during colitis was a consequence of enhanced epithelial cell loss." (PMID 30353167, 2019). "Correspondingly, exogenous β-HB improved colitis by reprogramming macrophages to an anti-inflammatory phenotype via a STAT-6-dependent signaling pathway." (PMID 39296504, 2024). "IL-13 secreted by ILC2 can induce epithelial cell SATA6 activation, which affects gut permeability and exacerbates experimental colitis, and STAT6 inhibition can reverse epithelial apoptosis and claudin-2 expression." (PMID 36032134, 2022). "Histological analysis also showed that blocking IL-13/STAT6 signaling prevented the deterioration of colitis." (PMID 36032134, 2022).
colitis (continued). "Leucrose, a natural sucrose isomer, suppresses DSS-induced colitis in mice by regulating macrophage polarization via JAK1/STAT6 signaling." (PMID 35663931, 2022). "In DSS-induced colitis mice, Wumeiwan regulated macrophage M1/M2 polarization in colonic macrophages to ameliorate colitis by activating the STAT6 signaling pathway." (PMID 36147340, 2022). "We reported a direct role of STAT6 in the induction and function of Treg cells during CAC development and suggest that STAT6 is a potential target for the modulation of immune response in colitis and CAC." (PMID 33919941, 2021). "The relative gene expressions of IFNγ, IL4, and STAT6 were significantly higher in the HA group in comparison to all groups with colitis (p < 0.01 for all comparisons with HA, with the exception of IL4: AC vs. HA, p < 0.05)." (PMID 33499240, 2021). "The relationship between STAT6 and immune cells was shown to be important in a model of oxazolone-induced colitis, where T cells, macrophages, and natural killer T cells exhibit an increased STAT6 phosphorylation during colitis development." (PMID 33919941, 2021). "Delayed mucosal regeneration with reduced expression of Lgr5 and C-myc has been observed previously in a model of colitis in STAT6−/− mice." (PMID 31877961, 2019). "As Stat6-deficient IEC were more susceptible to undergo apoptosis upon AOM challenge it was expected that during sporadic colitis-independent carcinogenesis Stat6−/− mice would exhibit reduced number of tumors." (PMID 30353167, 2019). "Wild-type (WT), Stat6 knockout (Stat6−/−), and intestinal epithelial cell-specific IL-4Rα knockout (Il-4rαΔIEC) mice were subjected to colitis-associated (AOM/DSS) and colitis-independent (sporadic) carcinogenesis." (PMID 30353167, 2019). "In line with a more severe form of colitis, histological analysis revealed increased tissue damage and epithelial ulceration in Stat6−/− mice." (PMID 30353167, 2019). "In line with this notion, Stat6−/− IEC proliferated significantly more during the healing phase of acute colitis." (PMID 30353167, 2019). "The finding that Stat6 loss can directly regulate IEC death in vivo, and therefore affect colitis severity and colorectal carcinogenesis is important to clarify its function during these two different conditions." (PMID 30353167, 2019). "In fact, in the oxazolone colitis model in which an increased epithelial cell, T cell, macrophage, and NKT cell STAT6 phosphorylation was observed, STAT6-deficient mice demonstrated a reduced disease phenotype." (PMID 30460209, 2018). "Studies also show that mesenteric lymph node cells from STAT6 (−/−) mice with colitis exhibited reduced secretion of IL-4, IL-13, and IFN-γ." (PMID 28752100, 2017). "It implicates that STAT6 plays important roles in regulating Th2-inducing cytokine production and altering epithelial barrier function in the pathogenesis of colitis." (PMID 28752100, 2017). "Inhibition of STAT6 function in colitis or tumor cells may present a novel strategy for treating CRC." (PMID 36768437, 2023). "In addition, it was found that miR-214-3p targets the STAT6 gene to regulate colitis, and both STAT3 and STAT6 belong to the same STAT family." (PMID 35743265, 2022). "In this study, we describe and prove the hypothesis that excessive CORT could exacerbate OXA-induced colitis by stimulating ILC2 and that blocking IL-13/STAT6 signaling could reduce CORT-induced exacerbation of colitis." (PMID 36032134, 2022). "Blocking the IL-13/STAT6 signaling pathway alleviated colitis in WRS and DEX-injected mice." (PMID 36032134, 2022). "In addition, the activation of STAT6 has been shown to lead to a reduction in the induction of Tregs, and thus it plays a critical role in the development of colitis in mice." (PMID 36397951, 2022). "Studies have reported that colitis is limited in STAT 6−/− mice and that deficiency of STAT6 may be helpful in improving IBD." (PMID 35634951, 2022).